PHACTR1 (phosphatase and actin regulator 1)
Diseases named in the same sentence as PHACTR1 in open-access papers (continued):
Sharing a sentence is not in itself a finding about the gene and the disease.
cardiovascular disease (10 papers, 2012 to 2024). "Other examples include artery eQTL for the cardiovascular diseases associated gene PHACTR1 (P = 8 × 10−10); the lysosomal acid lipase (LIPA) gene and microglia eQTL (P = 2 × 10−11); and the ABO blood group gene with plasma pQTL (P = 1 × 10−21)." (PMID 39563277, 2024). "Recent studies have increasingly demonstrated that phosphatase and actin regulator 1 (PHACTR1) gene polymorphisms are associated with cardiovascular disease (CVD) in different populations, including Mexicans, Caucasians and Chinese, etc.." (PMID 32420588, 2020). "Single-nucleotide polymorphisms (SNPs) in the protein phosphatase and actin regulator 1 gene (PHACTR1) have been associated with susceptibility to develop several diseases, including cardiovascular disease." (PMID 27517945, 2016). "In the PHACTR1 gene, two single-nucleotide polymorphisms (SNPs) have been associated with cardiovascular disease; the locations of these variants are 12825874 C > T (rs2026458) and 12903957 A > G (rs9349379)." (PMID 27517945, 2016). "Previous studies showed that PHACTR1 and SLC22A3 are involved in coronary vascular development and are key determinants of cardiovascular disease risk." (PMID 27893421, 2017). "Finally, future studies need to further expand the sample size and further investigate the specific mechanisms of PHACTR1 in cardiovascular disease through in vivo and in vitro experiments." (PMID 36364780, 2022). "Further studies are needed to validate whether PHACTR1 expression is decreased in plaque tissues from patients with cardiovascular diseases." (PMID 36364780, 2022). "This analysis also further demonstrates the correlation between PHACTR1 and cardiovascular disease." (PMID 36364780, 2022). "However, the role of PHACTR1 in cardiovascular disease is still controversial, especially its cell-type specificity." (PMID 36364780, 2022). "The mechanism that links PHACTR1 polymorphism with cardiovascular disease is not sufficiently described." (PMID 26086777, 2015). "Indeed, recent GWAS have identified common variants in several novel candidate genes for cardiovascular disease, such as the CDKN2A/2B/ANRIL gene cluster on 9p21.3, and PHACTR1 on chromosome 6p24.1." (PMID 22745674, 2012). "The role of PHACTR1 in the pathophysiolgy of cardiovascular disease remains to be elucidated." (PMID 22745674, 2012). "However, the role of PHACTR1 in endothelial function and cardiovascular disease is still unclear." (PMID 36364780, 2022). "PHACTR1 is a regulator of protein phosphatase 1 (PP1), an enzyme that regulates endothelial nitric oxide, an important modulator of cardiovascular disease." (PMID 22745674, 2012). "We speculate that PHACTR1 may be a new molecular target of RES in maintaining endothelial cell homeostasis and preventing cardiovascular disease." (PMID 36364780, 2022).
vascular disorder (4 papers, 2021 to 2023). A general term used to describe any disease affecting blood vessels]. "Addressing these open questions will definitely contribute to our deepened understanding of cell type-specific role of PHACTR1 in endothelial inflammation, innate immunity and associated vascular disorders." (PMID 36091033, 2022). "Emerging evidence has related vascular disorders such as SCeAD, SCoAD and FMD to the common variant rs9349379 at PHACTR1, likely mediated by ET-1 levels." (PMID 37214559, 2023).
cancer (3 papers, 2012 to 2023). A tumor composed of atypical neoplastic, often pleomorphic cells that invade other tissues. "TGF-β downregulates the expression of miR-584, a negative regulator of PHACTR1 (phosphatase and actin regulator 1), which in turn leads to actin rearrangement and cancer cell migration." (PMID 33321819, 2020). "Although Phactr1 and Galnt6 have not been directly implicated in trophoblast cell biology, they have been shown to regulate migration and invasion of cancer cells." (PMID 37417811, 2023).
tumor (2 papers, 2015 to 2025). "In some tumor cell lines, Phactr1 has been implicated in actin dynamics, cell motility and invasive behavior." (PMID 26098115, 2015).
PHACTR1 also shares sentences with these, for which no sentence is quoted: Arterial dissection (2 papers); migraine without aura (2); abdominal aortic aneurysm (1); acute myocardial infarction (1); and epileptic encephalopathy (1); arteriopathies (1); brain ischemia (1); chronic kidney disease (1); COVID-19 (1); developmental delay (1); dissection (1); generalized epilepsy (1); heart disease (1); heroin addiction (1); HIV-1 infection (1); hyperhomocysteinemia (1); hypertrophy (1); Hypsarrhythmia (1); inflammation (1); ischemic disease (1); large artery stroke (1); lymphoma (1); Moyamoya disease (1); neurodevelopmental disorder (1); osteoporosis (1); Parkinsonism (1); Respiratory tract infection (1); rheumatoid arthritis (1); tobacco use disorders (1); vascular hypertrophy (1).